CARD16 (caspase recruitment domain family member 16)
Description:
Caspase inhibitor. Acts as a regulator of procaspase-1/CASP1 activation implicated in the regulation of the proteolytic maturation of pro-interleukin-1 beta (IL1B) and its release during inflammation. Inhibits the release of IL1B in response to LPS in monocytes. Also induces NF-kappa-B activation during the pro-inflammatory cytokine response. Also able to inhibit CASP1-mediated neuronal cell death, TNF-, hypoxia-, UV-, and staurosporine-mediated cell death but not ER stress-mediated cell death. Acts by preventing activation of caspases CASP1 and CASP4, possibly by preventing the interaction between CASP1 and RIPK2.
Synonyms: Pseudo-ICE; COP; COP1; LLID-114769
Tractability: PROTAC: ubiquitination databases record sites on it; its protein half-life has been measured.
Gene: Protein-coding gene on chromosome 11 (105,039,092 to 105,101,431, reverse strand). Ensembl gene ENSG00000204397.
Subcellular location (Human Protein Atlas): Mitochondria
Gene Ontology:
Molecular function: CARD domain binding; caspase binding; cysteine-type endopeptidase inhibitor activity; identical protein binding; kinase binding; protein binding; cysteine-type endopeptidase activity; enzyme binding
Biological process: cellular response to lipopolysaccharide; negative regulation of interleukin-1 beta production; negative regulation of lipopolysaccharide-mediated signaling pathway; negative regulation of tumor necrosis factor-mediated signaling pathway; positive regulation of canonical NF-kappaB signal transduction; proteolysis; regulation of apoptotic process; regulation of interleukin-1 beta production
Cellular component: protease inhibitor complex; protein-containing complex
Genetic constraint (gnomAD): Loss-of-function variants: 7 observed, 11.33 expected, observed/expected ratio (o/e) 0.62, 90% interval 0.35 to 1.16. The upper end of that interval is the gene's LOEUF score, 1.16, which puts it in group 5 of 6, group 1 being the genes least tolerant of losing a copy. Missense variants: 121 observed, 114.36 expected, observed/expected ratio (o/e) 1.06, 90% interval 0.91 to 1.23. Synonymous variants: 43 observed, 40.58 expected, observed/expected ratio (o/e) 1.06, 90% interval 0.83 to 1.37.
Homologues: Orthologues: pig CASP1 (68% identical), mouse Casp1 (61% identical), rat Casp1 (58% identical), tropical clawed frog casp8 (21% identical), zebrafish casp8 (16% identical), Caenorhabditis elegans ced-3 (15% identical), Drosophila melanogaster Dronc (13% identical), Caenorhabditis elegans csp-1 (10% identical), Caenorhabditis elegans csp-2 (8% identical), Drosophila melanogaster Decay (7% identical), zebrafish casp20 (7% identical), tropical clawed frog XB5812047 (2% identical), and 2 more. Paralogues in human: CASP1 (92% identical), CARD18 (51% identical), CASP4 (28% identical), CASP5 (21% identical), CASP8 (20% identical), CASP9 (19% identical), CFLAR (18% identical), CASP12 (16% identical), CASP2 (13% identical), CASP10 (11% identical), CASP7 (9% identical), CASP3 (6% identical), and 4 more.
Diseases named in the same sentence as CARD16 in open-access papers:
CARD16 is named in the same sentence as 19 diseases in open-access papers, as found by Europe PMC text mining. Sharing a sentence is not in itself a finding about the gene and the disease. The quoted sentences say what the papers report.
atherosclerosis (1 paper, 2023). A disease characterized by the build-up of fatty material and calcium deposition in the arterial wall resulting in partial or complete occlusion of the arterial lumen. "In addition to Dpp4, there was an upregulation of a number of inflammation‐related genes including Card8, Card16, Gzma, Prf1, Il2rg, Il32, Cd52, and Ccl4 in CD4+ T cells isolated from patients with atherosclerosis." (PMID 36683148, 2023).
epilepsy (1 paper, 2023). A brain disorder characterized by episodes of abnormally increased neuronal discharge resulting in transient episodes of sensory or motor neurological dysfunction, or psychic dysfunction. "The other two genes associated with TSC and epilepsy were BHLHA15, a basic-loop-helix transcription factor and CARD16, an inhibitor of apoptosis; both of uncertain relevance to TSC pathogenesis." (PMID 37996417, 2023).
glioma (1 paper, 2021). A benign or malignant brain and spinal cord tumor that arises from glial cells (astrocytes, oligodendrocytes, ependymal cells). "We observed that the IRSs of PROS1, P2RY8, PLAU, CHI3L2, MSR1, CCR5, and TRIM38 were higher than its corresponding IRSs in low-grade glioma, while the IRSs of HAMP, CARD16, and S100A8 in high-grade glioma were lower than low-grade glioma." (PMID 34954691, 2021).
ovarian carcinoma (1 paper, 2022). A malignant neoplasm originating from the surface ovarian epithelium. "Furthermore, the deregulation of other downregulated genes following RBPMS knockout, including PDGFD, TES, CARD16, and KNF521, has been linked to the progression of many cancer types, and the role of these genes in the ovarian cancer setting should be investigated." (PMID 35008958, 2022).
CARD16 also shares sentences with these, for which no sentence is quoted: infection (15 papers); COVID-19 (4); mammary cancer (3); pertussis (3); cancer (2); malaria (2); viral diseases (2); adenocarcinoma (1); breast carcinoma (1); cholera (1); dengue (1); influenza infection (1); leukemia (1); shigellosis (1); tularemia (1).